SLC34A1 (solute carrier family 34 member 1)
Diseases named in the same sentence as SLC34A1 in open-access papers (continued):
Sharing a sentence is not in itself a finding about the gene and the disease.
chronic kidney disease (8 papers, 2021 to 2025). Impairment of the renal function secondary to chronic kidney damage persisting for three or more months. "In a recent long-term follow-up of 18 patients with CYP24A1 and SLC34A1 mutations, impaired kidney function at a mean age of 23.8 years was found in 77%, including two adults with end-stage renal disease." (PMID 34858904, 2021). "However, SLC34A1 mutations are associated with a high risk for chronic kidney disease (CKD), possibly due to nephrocalcinosis." (PMID 37660247, 2024). "Genome-wide-association studies identified SLC34A1 as a risk locus for chronic kidney disease." (PMID 35414099, 2022). "Interestingly, variants of Slc34a1 have been associated with chronic kidney disease in genome-wide association studies." (PMID 34737344, 2021). "The expression of SLC34A1 was tubule specific, and its expression showed downregulation in chronic kidney disease." (PMID 33627123, 2021).
rickets (8 papers, 2017 to 2025). Bone softening and weakening usually caused by deficiency or impaired metabolism of vitamin D. Deficiency of calcium, magnesium, or phosphorus may also cause rickets. "FRTS2 is characterized by phosphate wasting and rickets, and is caused by a mutation in SLC34A1, which encodes the phosphate transporter NaPi-IIa." (PMID 36431026, 2022). "Moreover, our patient harboured a pathogenic variant in the SLC34A1 gene encoding the renal sodium–inorganic PO4 cotransporter NaPi-IIa, thus prompting discussion regarding the pitfalls in the differential diagnosis of rickets in the era of next generation sequencing technologies." (PMID 40225330, 2025). "However, we also found variants in genes associated with primary hyperparathyroidism (GCM2), renal hypophosphatemia with or without rickets (SLC34A1, SLC34A3, SLC9A3R1, VDR, and CYP27B1), DiGeorge syndrome (TBX1 and NEBL), and hypophosphatasia (ALPL)." (PMID 38586466, 2024).
hypophosphatemic rickets (7 papers, 2020 to 2025). Rickets due to low serum phosphate concentrations, the cause of which can be nutritional or genetic. "Two siblings with autosomal recessive Fanconi's syndrome and hypophosphatemic rickets were found to have a duplication of 21 bp in SLC34A1, which is responsible for encoding for NpT2a." (PMID 39888445, 2025). "Such a digenic mechanism, with both heterozygous SLC34A1 and SLC34A3 mutations, has been postulated as the cause of hypophosphatemic rickets with renal stone disease in an American family." (PMID 34721296, 2021).
osteoporosis (7 papers, 2015 to 2025). A condition of reduced bone mass, with decreased cortical thickness and a decrease in the number and size of the trabeculae of cancellous bone (but normal chemical composition), resulting in increased fracture incidence. "Mutations in SLC34A1 have been reported to cause hypophosphatemic nephrolithiasis and osteoporosis in human." (PMID 35910217, 2022). "And one case with the pathogenic variant of SLC34A1 continued the treatment for osteoporosis." (PMID 39363361, 2024).
Fanconi syndrome (6 papers, 2015 to 2025). "In the case of SLC34A1 (Solute Carrier Family 34 Member 1), two mouse models of Slc34a1 deficiency either due to genetic deletion or to the spontaneous occurrence of the compound heterozygous mutations at p.(L499V) and p.(V528M) show no Fanconi syndrome." (PMID 32150856, 2020).
infantile hypercalcemia type 2 (5 papers, 2017 to 2026). "Inactivating mutations in SLC34A1 can cause three different diseases: HRs with Nephrolithiasis and Osteoporosis type 1 (NPHLOP1, MIM 612286), Fanconi Renotubular Syndrome type 2 (FRTS2, MIM 613388) and Infantile Hypercalcemia type 2 (HCINF2; MIM 616963)." (PMID 29280738, 2017).
urinary stone (3 papers, 2023 to 2025). "In addition, cortical macrophages in the kidney exhibit elevated expression of the phosphate transporter solute carrier family 34 member 1 (SLC34A1), enabling the active reabsorption of phosphate from the urinary filtrate and thereby mitigating the risk of urinary stone formation." (PMID 41050663, 2025).
autosomal dominant hypophosphatemia (2 papers, 2018 to 2019). "Here we report an autosomal dominant hypophosphatemia pedigree carrying a novel heterozygous mutation in SLC34A1." (PMID 31096470, 2019).
Calcium nephrolithiasis (2 papers, 2021 to 2022). The presence of calcium-containing calculi (stones) in the kidneys. "Our results indicated that rs578595 at WDR72, rs1037271 at DGKH, rs12654812 at SLC34A1, rs12539707 at HIBADH, and rs12626330 at CLDN14 were associated with the risk of calcium nephrolithiasis in Chinese Han population." (PMID 35910217, 2022). "Moreover, rs12654812 at SLC34A1 (p = 0.0427, OR = 1.170), rs12539707 at HIBADH (p = 0.0179, OR = 0.734), rs1037271 at DGKH (p = 0.0096, OR = 0.828) and rs12626330 at CLDN14 (p = 0.0080, OR = 1.213) indicated suggestive associations with calcium nephrolithiasis." (PMID 35910217, 2022).
hyperparathyroidism (2 papers, 2017 to 2020). Hyperfunction of the parathyroid glands resulting in the overproduction of parathyroid hormone. "The differential diagnosis consists in the hypocalciuric hypercalcaemia syndrome, types 2 (involving GNA11 gene) and 3 (involving AP2S1 gene); hyperparathyroidism; abnormalities of vitamin D metabolism, involving CYP24A1 and SLC34A1 genes; and reduced GFR." (PMID 28122587, 2017).
kidney damage (2 papers, 2024 to 2025). "A reduced glomerular filtration rate (GFR) was noted not only in IH patients with recessive CYP24A1 mutations but also in patients with a heterozygous SLC34A1 variant, suggesting that elevated 1,25(OH)2D3 levels may contribute to kidney damage." (PMID 41303235, 2025).
renal cell carcinoma (2 papers, 2022 to 2023). "This involved studying the relationship between SLC34A1 and its related gene mutations, phosphoprotein expression, DNA methylation, and immune cell infiltration to explore the value of SLC34A1 in the occurrence and development of renal cell carcinoma." (PMID 36978048, 2023).
renal Fanconi syndrome (2 papers, 2021 to 2025). "Loss-of-function mutation in protein-coding regions of SLC34A1 results in abnormal kidney function as renal Fanconi’s syndrome." (PMID 33627123, 2021).
vitamin D deficiency (2 papers, 2020 to 2025). A nutritional condition produced by a deficiency of VITAMIN D in the diet, insufficient production of vitamin D in the skin, inadequate absorption of vitamin D from the diet, or abnormal conversion of vitamin D to its bioactive metabolites. "Whether monoallelic variants of the SLC34A1 may favour the development of proximal renal tubular dysfunction in subjects with vitamin D deficiency needs to be evaluated in further studies." (PMID 40225330, 2025).
atopic dermatitis (1 paper, 2025). "Phenome-wide association study data suggested that modulating DGKD, CASR, CYP24A1, or SLC34A1 may result in target-mediated adverse effects including alterations in serum bilirubin, inflammatory bowel disease, migraine, atopic dermatitis, and eczematous phenotypes." (PMID 40372791, 2025).
cystinosis (1 paper, 2021). Cystinosis is a metabolic disease characterized by an accumulation of cystine inside the lysosomes, causing damage in different organs and tissues, particularly in the kidneys and eyes. "Instead, they found a major reduction in the surface localization of the phosphate transport (Slc34A1 aka NaPi2a), accounting for the reduced renal phosphate uptake in cystinosis." (PMID 35011573, 2021).
kidney cancer (1 paper, 2020). Primary or metastatic malignant neoplasm involving the kidney. "In kidney cancer, SLC22A6, SLC22A7, SLC22A13, SLC25A4, SLC34A1, and SLC44A4 were significantly downregulated." (PMID 32461965, 2020).
Obesity (1 paper, 2022). Accumulation of substantial excess body fat. "The mEC1 population showed an obesity-induced downregulation of transporters of major ions (Slc34a1, Slc4a4, Slc22a8, Slc13a1, Slc22a18 and Slc5a12), neutral amino acids (Slc6a19) and glucose (Slc5a2)." (PMID 36400935, 2022).
renal tubular disorders (1 paper, 2026). "Pathogenic variants in the SLC34A1 gene give rise to a rare and heterogeneous spectrum of renal tubular disorders, emphasizing the critical importance of specialized clinical expertise for accurate diagnosis and management." (PMID 41543768, 2026).
cancer (6 papers, 2017 to 2023). A tumor composed of atypical neoplastic, often pleomorphic cells that invade other tissues. "In patients with ccRCC, lower expression levels of SLC34A1 tend to be associated with more advanced cancer stages." (PMID 36978048, 2023). "This suggests that the decreased expression of SLC34A1 may be linked to cancer progression." (PMID 36978048, 2023). "Surprisingly, most of the enhancers of these genes (except SLC34A1) were hypomethylated, and the methylation status of them are able to distinguish the patient survival independently, suggesting an important mechanism of building up the cancer risk through turning on a group of enhancers." (PMID 28621677, 2017). "Among the various cancers examined, SLC22A6, SLC22A7, SLC22A13, SLC25A4, and SLC34A1 were significantly downregulated, while SLC44A4 showed different expression patterns in different cancers (upregulated or downregulated)." (PMID 32461965, 2020). "The expression levels of SLC22A6, SLC22A13, SLC25A4, SLC34A1, and SLC44A4 were significantly correlated with the clinical stage of the cancer." (PMID 32461965, 2020). "We used the Oncomine database to analyze the expression levels of SLC22A6, SLC22A7, SLC22A13, SLC25A4, SLC34A1, and SLC44A4 in various cancers and their normal tissues." (PMID 32461965, 2020).
kidney disease (4 papers, 2023 to 2024). "Stable-effect variants mapped to Mendelian kidney disease genes (SLC34A1), but also to creatinine metabolism (CPS1, SLC22A229,30) in line with differential expression in muscle." (PMID 39567532, 2024).
SLC34A1 also shares sentences with these, for which no sentence is quoted: Fanconi renotubular syndrome 2 (4 papers); hereditary hypophosphatemic rickets (3); hereditary hypophosphatemic rickets with hypercalciuria (3); tumor (3); Autosomal recessive infantile hypercalcemia (2); Failure to thrive (2); infection (2); kidney failure (2); pulmonary alveolar microlithiasis (2); Sotos syndrome (2); autosomal recessive hypophosphatemic rickets (1); calcium-phosphorus metabolic disorder (1); clear cell renal cell carcinoma (1); cognitive decline (1); DiGeorge syndrome (1); end-stage renal disease (1); epilepsy (1); hydronephrosis (1); hypertensive chronic kidney disease (1); hypophosphatasia (1); inflammatory bowel disease (1); iron deficiency (1); McCune-Albright syndrome (1); migraine (1); muscle atrophy (1); opsismodysplasia (1); osteomalacia (1); Osteopenia (1); primary hyperparathyroidism (1); Raine syndrome (1).
A further 5 diseases each share a sentence with SLC34A1 in 1 paper.